TMPRSS2 (transmembrane serine protease 2)
Diseases named in the same sentence as TMPRSS2 in open-access papers (continued):
Sharing a sentence is not in itself a finding about the gene and the disease.
prostate carcinoma (continued). "It is well known that about the half of prostate cancers carry a gene fusion, which links the androgen-regulated serine protease TMPRSS2 with the ETS-transcription factor ERG resulting in an androgen-related expression of ERG with subsequent dysregulation of more than 1600 ERG target genes." (PMID 29304771, 2018). "The meta-analysis findings suggested that the TMPRSS2-ERG fusion gene might be a predictive marker for prostate cancer patients, and might be valuable for assessing the characteristics of prostate cancer for individualized treatment and prognosis evaluation." (PMID 30459527, 2018). "Furthermore, we performed PCR using DNAs extracted from prostate cancer tissues and detected TMPRSS2–ERG gene fusion in 15 of 49 prostate cancers." (PMID 30291252, 2018). "The TMPRSS2–ERG fusion gene is one of the most frequently over-expressed genes in prostate cancer." (PMID 28382513, 2017). "TMPRSS2:ERG is growth promoting in VCaP prostate cancer cells and in mouse models, although whether androgen or 1,25D(OH)2D3 induction of the already highly expressed TMPRSS2:ERG increases ERG activity had not been examined." (PMID 28591703, 2017). "The fusion mutations from tumor samples appear to have various iFCR values and, interestingly, the well-studied prostate cancer fusion TMPRSS2-ERG was closed to the fusions of cancer cell lines and appears to have higher iFCR values and expression levels in all three independent patients." (PMID 29181411, 2017). "Given that TMPRSS2-ERG increases both the migration in vitro and the subcutaneous tumor development, we then tested whether TMPRSS2-ERG could be taking part in the bone metastasis formation of prostate cancer cells in vivo." (PMID 28055969, 2017). "Given that the patient data demonstrate heterogeneity of ERG expression in TMPRSS2:ERG positive prostate cancer, we cannot completely exclude the possibility that VDR-mediated induction of ERG will cause an increase in ERG activity in cells with low basal levels of TMPRSS2:ERG expression." (PMID 28591703, 2017). "Interestingly, EGF can interact with Src tyrosine kinase pathway in the induction of EMT in TMPRSS2-ERG positive prostate cancers." (PMID 28430640, 2017). "TMPRSS2:ERG (T/E) gene fusions are present in approximately 50% of all prostate cancer (PCa) cases." (PMID 28445989, 2017). "The question of whether VDR agonist would be beneficial or harmful in TMPRSS2:ERG positive prostate cancer has been an important question since we observed that VDR induces its expression." (PMID 28591703, 2017). "The well known prostate cancer fusion TMPRSS2-ERG has been validated in Samples 1T, 5T and 13T." (PMID 28114882, 2017). "For example, it has been previously reported that the oncogenic transcription factor ERG (ETS-related gene), is up regulated in prostate cancer due to the fusion with the 5′ region of the TMPRSS2 (trans-membrane protease, serine 2) gene that contains an androgen responsive promoter element." (PMID 28851357, 2017). "We applied HOCUS to TCGA prostate adenocarcinoma (PRAD) copy number data because prostate cancers are known to harbor significant copy number events over the evolution of the tumor including AR amplifications, TMPRSS2-ERG fusions, and even whole genome level events such as chromoplexy." (PMID 28359308, 2017). "Specifically, the TMPRSS2-ERG is the most studied chimeric transcript in prostate cancer." (PMID 29181411, 2017). "TMPRSS2 is upregulated by androgenic hormone in prostate cancer cells." (PMID 28086212, 2017). "In addition, TMPRSS2-ERG fusion is present in 40%–80% of prostate cancers, overexpression of estrogen-regulated gene (ERG) due to gene fusion is associated with a more aggressive phenotype in prostate cancer." (PMID 28086212, 2017). "TMPRSS2:ERG fusions are frequent in prostate cancer, and occur predominantly in young patients." (PMID 27530104, 2016).
prostate carcinoma (continued). "The data of this study suggest that pure “fusion-type” prostate cancer, where TMPRSS2:ERG fusions constitute a potential initiating event, may occur in not more than one third of all prostate cancer foci." (PMID 27530104, 2016). "To determine whether urinary EVs could be used to examine other genes associated with prostate cancer we investigated the differential expression of androgen receptor (AR), BIRC5, ERG, PCA3, TMPRSS2:ERG and TMPRSS2 in Bx Pos versus Bx Neg patients." (PMID 27144529, 2016). "The AR-inhibitory function of PRMT5 is restricted to TMPRSS2:ERG-positive prostate cancer cells." (PMID 27183006, 2016). "Importantly, prostate cancer-associated SPOP mutants fail to induce ERG degradation, whereas the majority of TMPRSS2-ERG fusions encoding N-terminal truncated ERG proteins are resistant to SPOP-mediated degradation." (PMID 27200299, 2016). "The TMPRSS2:ERG fusion represents the most common genomic rearrangement in prostate cancer." (PMID 27530104, 2016). "TMPRSS2-ERG has been proposed to be a prognostic marker for prostate cancer." (PMID 27276682, 2016). "In support of this speculation, previous studies report that TMPRSS2/ERG fusion is indeed a predictor of favorable outcome for prostate cancer patients." (PMID 27191272, 2016). "In order to investigate if 11KT and 11KDHT demonstrate androgenic activity on endogenous AR-regulated genes, the mRNA expression levels of KLK3 (NM_001030047), FKBP5 (NM_001145775) and TMPRSS2 (NM_001135099) were assessed in two androgen dependent prostate cancer cell lines, LNCaP and VCaP." (PMID 27442248, 2016). "This provides a rationale for targeting PRMT5 in TMPRSS2:ERG positive prostate cancers." (PMID 27183006, 2016). "Further, inhibition of TMPRSS2 suppresses prostate cancer metastasis in vivo." (PMID 26872377, 2016). "This Tmprss2-CreERT2 knock-in strain is highly efficient and allows precise control over the timing of introducing gene alterations in the mouse prostate and colon, and accurately mimics the late onset of human prostate cancer and colon cancer." (PMID 27536883, 2016). "While therapeutic targeting of transcription factor oncogenes is intrinsically challenging, on the basis of the interaction of ERG with the DNA repair enzyme PARP1 and DNA protein kinase DNA-PKc, use of PARP inhibitors was shown to inhibit growth of TMPRSS2-ERG-positive prostate cancer xenografts." (PMID 26684754, 2015). "About half of all prostate cancers harbor the TMPRSS2:ERG (T2E) gene fusion." (PMID 26692910, 2015). "Furthermore, the manipulation of PDE4D7 suggests a strategy to selectively treat TMPRSS2-ERG fusion-positive prostate cancers." (PMID 26575822, 2015). "This would represent a double-edged sword for prostate cancer survival and progression, as the inhibition observed could favor resistance to apoptosis by siRNA TMPRSS2-ERG treatment or decrease dedifferentiation and therefore enhance cancer cell death." (PMID 25933120, 2015). "Another common genomic aberration in prostate cancer was various fusion genes at the TMPRSS2 locus." (PMID 25915538, 2015). "Majority of prostate cancer (PCa) patients carry TMPRSS2/ERG (T/E) fusion genes and there has been tremendous interest in understanding how the T/E fusion may promote progression of PCa." (PMID 25749044, 2015). "As the TMPRSS2-ERG fusion is the most common genomic alteration in prostate cancer, and cell migration is a key component of metastasis, the high-affinity ERK2/ERG interaction represents a potential target for small molecule inhibition during prostate cancer treatment." (PMID 25885538, 2015). "Of these, overexpression of the ETS-related gene (ERG), resulting from the fusion of ERG coding sequences to the androgen-responsive TMPRSS2 gene, represents the most common subtype, with a prevalence of approximately 50% in clinically localized prostate cancers." (PMID 25889691, 2015).
prostate carcinoma (continued). "This suggests that proliferation may be stimulated by AR independent mechanisms in castration resistant prostate cancer through TMPRSS2-ERG activation." (PMID 25933120, 2015). "The TMPRSS2-ERG gene fusion is now a specific biomarker of prostate cancer." (PMID 26035298, 2015). "The discovery of the chromosomal rearrangement leading to TMPRSS2-ERG fusion oncogene, present in more than 50% cases of prostate cancers, has opened important diagnostic and therapeutic perspectives for the treatment of one of the most frequent epithelial tumours in men." (PMID 25933120, 2015). "Further, TMPRSS2-ERG gene fusion holds promise as a potential prostate cancer biomarker." (PMID 26683658, 2015). "TMPRSS2 contributes to the invasion and metastasis of prostate cancer." (PMID 26683658, 2015). "Prostate cancers are characterized by over-expression of the ETS transcription factor ERG as a result of a somatically acquired fusion event to the regulatory region of the TMPRSS2 gene." (PMID 26172920, 2015). "Additionally, VCaP cells belong to a subtype of prostate cancer that possesses the TMPRSS2:ERG fusion, resulting in the AR driven expression of ERG." (PMID 26571387, 2015). "EZH2 is a target of ERG, and therefore overexpressed in TMPRSS2:ERG-positive prostate cancers." (PMID 25496077, 2014). "TMPRSS2:ETS gene fusions are present in around 50% of prostate cancers in surgical case series." (PMID 25496077, 2014). "The TMPRSS2-ERG gene fusion is found in approximately half of all prostate cancers." (PMID 24505269, 2014). "Our observation of conserved NKX3.1 binding elements in the TMPRSS2 promoter prompted us to examine the hypothesis that NKX3.1 is a repressor of ERG in the TMPRSS2-ERG fusion genomic context in prostate cancer." (PMID 24418414, 2014). "Here, a member of the ETS transcription factor family, ERG that is typically expressed at very low levels in benign prostate epithelial cells is fused with the androgen-responsive TMPRSS2 (transmembrane protease serine 2) to generate a prostate cancer oncogene." (PMID 25988147, 2014). "Therefore, it is understandable that miRNA mediated control of AR is lost in TMPRSS2-ERG positive prostate cancer and ELAVL1 stabilizes the expression of AR and ERBB2 which synchronously trigger the expression of cancer promoting genes." (PMID 24739220, 2014). "Much has been learned about the androgenic regulation of TMPRSS2 promoter in prostate cancer." (PMID 24418414, 2014). "The role of AR in prostate cancer initiation is accentuated by the seminal discovery that the oncogenic ETS family transcription factors, such as ERG and ETV1, are translocated to the loci of androgen regulated genes including TMPRSS2 in approximately 50% of all human prostate cancers." (PMID 24508459, 2014). "Moreover, this study has identified associations between TMPRSS2-ERG and stromal changes, previously identified as biomarkers predicting a worse prognosis of prostate cancer patients." (PMID 24505269, 2014). "As a result, TDRD1 becomes transcriptionally activated in TMPRSS2:ERG-positive prostate cancer." (PMID 23555854, 2013). "The TMPRSS2/ERG (T/E) fusion gene is present in the majority of all prostate cancers (PCa)." (PMID 23554889, 2013). "Analysis of the prostate cancer transcriptome performed by us and others demonstrated that tumors harboring the TMPRSS2:ERG fusion share a unique gene expression profile which significantly differs from profiles of benign prostate tissue and malignant tumors lacking the fusion." (PMID 23555854, 2013). "Interestingly, much rigorous debate has surrounded the validity of this lone marker in determining prostate cancer recurrence and mortality, and recent literature calls for a reevaluation of using TMPRSS2:ETS fusions alone as prognostic indicators." (PMID 24018887, 2013).
prostate carcinoma (continued). "To test if TDRD1 may interact with PIWI proteins in TMPRSS2:ERG-positive prostate cancer and thus contribute to the piRNA pathway activity, we measured the mRNA expression of human PIWIL genes in prostate cancer cell lines." (PMID 23555854, 2013). "We propose that this epigenetic consequence of the TMPRSS2:ERG fusion represents a novel mechanism which may explain part of the transcriptional modulation induced by ERG in human prostate cancer." (PMID 23555854, 2013). "AR stimulates the expression of TMPRSS2: ERG, a common gene fusion associated with prostate cancer." (PMID 23466879, 2013). "We propose the model that moderate AR gain in a TMPRSS2:ERG fusion-positive primary prostate cancer might synergistically enhance the expression of ERG, which gives growth advantage to those cells with moderate AR gain." (PMID 24098661, 2013). "The formation of the TMPRSS2-ERG gene fusion that occurs in about 50% of prostate cancers has been shown to be facilitated by androgen signaling which induces proximity of the TMPRSS2 and ERG genomic loci and then exposure to gamma irradiation which causes DNA double-strand breaks." (PMID 24261984, 2013). "We analyzed 110 primary prostate cancer samples, 70 metastatic tumor samples from 11 patients, and 27 xenograft tissues derived from 22 advanced prostate cancer patients using fluorescence in situ hybridization (FISH) analysis with probes targeting the TMPRSS2/ERG, PTEN, and AR gene loci." (PMID 24098661, 2013). "We tested whether our approach would allow distinguishing TMPRSS2-ERG-positive from TMPRSS2-ERG-negative prostate cancers." (PMID 23561577, 2013). "An example of this is the TMPRSS2-ERG fusion gene in prostate cancer." (PMID 24349831, 2013). "Indeed, the TMPRSS2:ERG fusion RNA is shown to be detectable in the urine of men with prostate cancer." (PMID 24133629, 2013). "Of note, the average level of TDRD1 promoter methylation was inversely correlated with TDRD1 mRNA levels across all 93 samples (ρ = -0.57), suggesting that loss of promoter methylation substantially contributes to TDRD1 overexpression in TMPRSS2:ERG fusion-positive prostate cancer." (PMID 23555854, 2013). "The important regulatory role of androgens on the TMPRSS2:ETS fusion via interaction with the androgen receptor (AR) enables a new promise for a potential role of the gene fusions in predicting the emergence of castration resistant prostate cancer (CRPC)." (PMID 24018887, 2013). "For instance, all 3 CTCs from patient 1 expressed high levels of SPINK1, a transcript and protein identified as elevated in TMPRSS2-ERG fusion negative prostate cancers and associated with aggressive prostate cancer." (PMID 23145101, 2012). "The fact that androgen treatment alone can induce TMPRSS2: ERG fusion in the prostate cancer, LNCaP, cell line suggests that these cells may contain a detective ATM/ATR DNA damage checkpoint." (PMID 23272087, 2012). "MYB-NFIB in head and neck tumors, TMPRSS2-ERG/ETS in prostate cancer, and EML4-ALK in lung cancer." (PMID 22496636, 2012). "Tmprss2 is a transmembrane signalling protein that is upregulated in prostate cancer." (PMID 22260314, 2012). "More importantly, both studies demonstrated that transient androgen treatment resulted in induction of TMPRSS2: ERG fusion in prostate cancer cells, suggesting that androgen may play an important role in prostate cancer predisposition." (PMID 23272087, 2012). "Setlur and colleagues identified a subtype of prostate cancer characterized by the fusion of the 5′-untranslated region of the androgen-regulated transmembrane protease serine 2 (TMPRSS2) promoter with erythroblast transformation-specific transcription factor family members (TMPRSS2-ER)." (PMID 22615778, 2012).
prostate carcinoma (continued). "In addition to prevailing alterations in AR expression and function, approximately half of prostate cancer samples harbor an oncogenic gene fusion combining androgen-regulated transmembrane protease serine 2 (TMPRSS2) with oncogenic ETS transcription factors." (PMID 22761906, 2012). "Moreover, disulfiram-sunitinib cotreatment induced apoptosis whereas neither of the compounds alone promoted programmed cell death in TMPRSS2-ERG fusion positive VCaP prostate cancer cells." (PMID 23251544, 2012). "Additional studies using TMPRSS2-ERG models will aid in defining basic mechanisms of action and of synergism with defined mutations, as well as helping to establish accurate preclinical models for prostate cancer treatment." (PMID 22860005, 2012). "TMPRSS2-ERG fusion is the most common known gene rearrangement in prostate carcinoma." (PMID 21731703, 2011). "Hence, it appears that EMT and invasion are general processes which are executed by TMPRSS2/ERG in prostate cancer, and which are achieved by diverse mechanisms." (PMID 21747944, 2011). "In this study, we found PSMA was downregulated by TMPRSS2-ERG fusion in VCaP prostate cancer cells." (PMID 21731703, 2011). "Although TMPRSS2-ERG is also found in 50% of prostate cancer specimens, it is unknown if, or to what extent these populations overlap." (PMID 21731703, 2011). "The fusion of these genes can be detected in urine, and this TMPRSS2-ERG gene fusion rearrangement may aid in predicting prostate cancer development." (PMID 24213111, 2011). "Since PSMA is a promising target for prostate cancer therapy and imaging, further elucidation of the relationship between TMPRSS2 gene fusions and PSMA could reveal novel pathways for enhancing targeted prostate cancer treatment." (PMID 21731703, 2011). "The overall data, therefore, indicates that the TMPRSS2-ERG fusion gene and the consequent ERG and CRISP3 overexpression are associated with pathological features related with locally advanced disease in patients with clinically localized prostate cancer." (PMID 21814574, 2011). "Of those, the TMPRSS2-ERG fusion is the most common known gene rearrangement in prostate cancer." (PMID 21731703, 2011). "Overexpression of the TMPRSS2-ERG fusion gene has been reported in 40–70% of prostate cancer cases." (PMID 21298110, 2011). "Understanding the complexity of isoform splicing in cancer may not only add insight into biology, but may also provide useful prognostic information as it has been suggested that some TMPRSS2-ERG isoforms play a distinct role in prostate cancer development." (PMID 20964841, 2010). "We hypothesized that the immunomagnetic enrichment method described herein could be used together with PCA3 and TMPRSS2:ERG assays to specifically detect CTCs in advanced prostate cancer." (PMID 20598135, 2010). "Detection of PCA3 and/or TMPRSS2:ERG mRNA in whole blood could potentially be used as a prognostic indicator of aggressive prostate cancer." (PMID 20598135, 2010). "It is therefore a reasonable hypothesis that therapeutic modalities targeting these pathways may be well suited for TMPRSS2–ERG fusion-positive prostate cancer patients." (PMID 20068566, 2010). "This study supports other evidence that TMPRSS2–ERG fusion status may have important predictive implications of such therapies in the efficacious treatment of prostate cancer." (PMID 20068566, 2010). "A very promising and highly prostate cancer specific marker is the fusion transcript TMPRSS2:ERG." (PMID 24281166, 2010). "The clinical significance of the presence of the TMPRSS2:ERG gene fusion product on prostate cancer presentation and progression is not fully understood, but studies to date suggest that this may be a biomarker of risk." (PMID 18781147, 2008). "No direct role for TMPRSS2 is currently known for prostate cancer susceptibility." (PMID 40198231, 2025).